AR (androgen receptor)
Diseases named in the same sentence as AR in open-access papers (continued):
Sharing a sentence is not in itself a finding about the gene and the disease.
prostate carcinoma (continued). "Androgen signalling, through the transcription factor androgen receptor (AR), is vital to all stages of prostate development and most prostate cancer progression." (PMID 37435460, 2022). "The AR is already a therapeutic target for prostate cancer and is also emerging as a new marker and potential therapeutic target for breast cancer." (PMID 35563746, 2022). "We demonstrated for the first time that tadalafil can modulate AR expression in prostate cancer cells in vitro, and it can induce the stabilization and reduce the degradation of AR." (PMID 35457011, 2022). "The AR signaling is one of the critical pathways involved in the prostate cancer formation and progression." (PMID 35563824, 2022). "Silencing of SENP1 has also been reported to suppress the expression of several AR target genes and to inhibit androgen-stimulated proliferation of LNCaP cells, thus the SUMOylation pathway is a potential therapeutic target for prostate cancer." (PMID 37435453, 2022). "While the role of AR is well established in prostate cancer (PCa), its function in BC remains incompletely understood." (PMID 36376977, 2022). "Barfeld and colleagues described an antagonistic relationship between MYC and AR, and showed that androgen stimulation of hormone-sensitive prostate cancer cell lines led to a reduction in MYC at the transcript and protein levels." (PMID 36212399, 2022). "Our study also provides a deeper understanding of the AR activity in the neuroendocrine transition of prostate cancer cells and allows future implications for anti-tumor therapies." (PMID 36033483, 2022). "AU-15330 induces potent inhibition of tumour growth in xenograft models of prostate cancer and synergizes with the AR antagonist enzalutamide, even inducing disease remission in castration-resistant prostate cancer (CRPC) models without toxicity." (PMID 34937944, 2022). "Taken together, targeting cell cycle-related regulators as well as AR is a promising therapeutic approach in the treatment of androgen-dependent prostate cancer cells." (PMID 36482936, 2022). "Throughout the entire course of the disease, prostate cancer cells are dependent on the androgen receptor (AR) signalling." (PMID 36819799, 2022). "MYB-overexpressing prostate cancer cells retain AR in the nucleus, even in androgen-deprived conditions, leading to enhanced transcriptional activity." (PMID 36551557, 2022). "For example, lnc-LBCS directly interacts with hnRNPK and forms a complex with hnRNPK and AR mRNA to inhibit AR translation efficiency and cancer progression in castrated prostate cancer research." (PMID 35571069, 2022). "Given these distinct mechanisms of AR regulation, BET inhibitor resistant prostate cancers demonstrated reactivation of AR signaling via CDK9-mediated phosphorylation of AR." (PMID 36139513, 2022). "The AR is specifically targeted in AR-sensitive cancers, for example the use of the anti-androgenic drug flutamide in treating prostate cancer." (PMID 36090961, 2022). "About 90% of diagnosed prostate cancers are androgen-dependent, and thus one of the most effective therapies is hormone therapy that reduces serum androgen levels and androgen receptor inhibition." (PMID 35055079, 2022). "There is a close relationship between miRNAs and androgen receptor (AR) signaling in enhancing prostate cancer progression." (PMID 35236381, 2022). "Abnormal AR functioning has been identified in numerous diseases, specifically in prostate cancer (PCa)." (PMID 35163477, 2022). "Apalutamide (APA) is a next-generation androgen receptor antagonist for the treatment of advanced prostate cancer." (PMID 35751683, 2022).
prostate carcinoma (continued). "We reveal that Janus kinase (JAK)–signal transducer and activator of transcription (STAT) signaling is a crucial executor in promoting lineage plasticity-driven androgen receptor (AR)-targeted therapy resistance in prostate cancer." (PMID 36065066, 2022). "The activation of the androgen receptor (AR) pathway is crucial in the progression of human prostate cancer." (PMID 35444697, 2022). "CRISPR deletion of NR2F1 was able to restore enzalutamide sensitivity in androgen receptor (AR)-positive prostate cancer LNCaP cell with chromodomain helicase DNA-binding protein 1 (CHD1) knockdown." (PMID 36230565, 2022). "In the present study, for the first time, we found a novel function of TR3, which controls AR splicing events in prostate cancer cells." (PMID 35454821, 2022). "Androgen deprivation therapy (ADT) directly targeting AR-expressing prostate tumor cells fails in most prostate cancer patients who consequently develop castration-resistant prostate cancer (CRPC), an incurable disease." (PMID 36323713, 2022). "Prostate-specific antigen (PSA) expression is the clinically validated downstream indicator of androgen receptor activity and an important marker for prostate cancer progression in patients." (PMID 35630591, 2022). "Prostate cancer cells were transduced by our prostate cancer-specific biosensor and cultured; the target (androgen receptor activity) was monitored in real-time upon exposure to an anticancer drug (antiandrogen)." (PMID 34976196, 2022). "Several kinds of endocrine therapies including castration, gonadotropin-releasing hormone analogues and AR antagonists are used as androgen deprivation therapy (ADT) for prostate cancer." (PMID 35954308, 2022). "Androgens act as ligands that bind to AR, and the activated AR binds to the DNA sequences of downstream genes and initiates the expression of a series of genes that promote prostate cancer progression." (PMID 35935969, 2022). "Prostate cancer progression is mainly driven by the androgen receptor (AR) signaling pathway and its inhibition has been the cornerstone in the treatment of patients harboring this disease." (PMID 36551557, 2022). "The possibility of combining BETi with immunotherapy or AR targeting medicines to treat advanced prostate cancer will be determined by the results of ongoing clinical trials." (PMID 36034650, 2022). "Androgen receptor (AR), a strong driver of proliferation in prostate cancer, was downregulated following the treatment with kahweol acetate and cafestol." (PMID 36364160, 2022). "LuCaP PDX tumors developed from a series of prostate cancer metastases are well-established model systems representing several phenotypic characteristics of clinical PC, including differential androgen receptor activity." (PMID 35406510, 2022). "Correlations between altered androgen, IGF1, and Wnt/β-catenin signaling are also identified in human prostate cancer samples, uncovering a dynamic regulatory loop initiated by the AR through prostate cancer development." (PMID 35902588, 2022). "Known etiologies of prostate cancer include but are not limited to androgen/androgen receptor (AR), EMT, genetics, and pathway alterations." (PMID 36294924, 2022). "The miR-124 also targets AR transcription, acting as a tumor suppressor that widely limits prostate cancer growth." (PMID 35456428, 2022).
prostate carcinoma (continued). "Altogether, our study revealed an intricate crosstalk between the AR, MYC, FOXA1 and RNA Pol II resulting in a corrupted AR transcriptional program and promoting prostate cancer initiation and progression to the mCRPC stage." (PMID 35562350, 2022). "As there is a profound paucity of effective treatments for mCRPC patients, research into methods of targeting non-AR transcription factors in prostate cancer is critical." (PMID 35547880, 2022). "RNase H2 i treatment was demonstrated to downregulate AR and AR-V7 expression and upregulate γH2AX expression in prostate cancer cells." (PMID 36923313, 2022). "As the prostate cancer turned castration-resistant, multimodal therapies including taxane- and platinum-based chemotherapy, androgen-receptor antagonist inhibitors, radiotherapy and radium-233 were introduced." (PMID 35183184, 2022). "EPI-001, an androgen receptor (AR) antagonist-like prostate cancer treatment drug developed by Essa Pharma, can block the transactivation of the AR N-terminal domain (AR-NTD)." (PMID 36431829, 2022). "In prostate cancer cells, AR enhances aerobic glycolysis by rapidly promoting glucose uptake and usage, promoting mitochondrial respiration, and stimulating mitochondrial biogenesis." (PMID 36551308, 2022). "AR drives the expression of metabolic pathways to support high levels of O-GlcNAcylation in prostate cancer cells." (PMID 35164752, 2022). "Androgen receptor signaling inhibitors (ARSi) are currently the primary treatment regimen for advanced prostate cancer." (PMID 35087237, 2022). "Androgen receptor can be activated by its natural agonists testosterone and dihydrotestosterone and is the major target for prostate cancer therapy." (PMID 35966880, 2022). "For example, the emergence of distinct transcription factor complexes other than the androgen receptor (AR) has been reported in prostate cancer (PC) progression." (PMID 36263200, 2022). "In fact, enzalutamide, an oral AR antagonist used for prostate cancer treatment, was shown to induce apoptosis in several GBM cell lines and decrease tumour growth in mouse models." (PMID 35661403, 2022). "Here, we summarize the interplay between Src and AR signalling during castrate-resistant prostate cancer progression to provide insights on possible approaches to treat prostate cancer patients." (PMID 35832549, 2022). "Therapies that target the activity of the androgen receptor (AR) remain central to the treatment of prostate cancer (PCa), as AR signaling is known to be a primary factor for driving PCa growth, progression, and metastasis." (PMID 35018219, 2022). "The mechanisms of prostate cancer progression to CRPC associated with proteins are complex and mainly involve the AR-dependent and AR-independent mechanisms." (PMID 35756667, 2022). "Prostate cancer cells can adapt to androgen deprivation and restore androgen receptor signaling, eventually progressing to CRPC, even CRPC-NE, which is a lethal subtype of PCa with extremely poor survival rate." (PMID 36686485, 2022). "The androgen receptor (AR) plays a critical role for the survival and proliferation of prostate cancer cells." (PMID 36115838, 2022). "All aspects of prostate cancer evolution are closely related to androgen levels and the status of the androgen receptor (AR)." (PMID 36362304, 2022). "AR plays a critical role in metabolism and reproduction and is the main target for the development of prostate cancer treatments." (PMID 35955864, 2022). "A human prostate cancer cell line LNCaP containing the full-length AR gene was injected into NOD/SCID mice to establish an in vivo tumor model." (PMID 35712699, 2022). "Androgen receptor-regulated signaling pathways play a key role in the progression of the prostate cancer in which androgen-metabolizing enzymes CYP3A4, CYP3A5, and CYP3A43 are expressed." (PMID 36359206, 2022).
prostate carcinoma (continued). "In our previous study, we reported that Cyclin-dependent kinase 5 (CDK5), a unique member of Cyclin-dependent kinases, regulates AR activation during the development of prostate cancer." (PMID 36482936, 2022). "The LNCaP cells, which express a mutant form of the AR, are often used as a model of early-stage prostate cancers." (PMID 36175875, 2022). "Galeterone therapy in prostate cancer models has led to a considerable decrease in the levels of both full-length AR and AR-V7, according to preclinical in vitro and in vivo findings." (PMID 36551557, 2022). "Among the tested cancer cells, the human nonsmall‐cell lung cancer H460 and the androgen receptor positive and hormone‐insensitive human prostate cancer DU145 exhibited very high sensitivity to the mannose‐ and galactose‐derived molecules: Cor‐man and Cor‐gal." (PMID 35253390, 2022). "Taken together, these data suggest that the GalNAc-containing glycocalyx is functionally important for prostate cancer cell motility and metastasis when AR signaling is lost or inhibited." (PMID 35963852, 2022). "Studies using a variety of prostate cancer cell lines later demonstrated that FOXA1 overexpression or knock-down reprograms the AR cistrome." (PMID 36212399, 2022). "One direct AR downstream target that promotes prostate cancer progression is the calcium-calmodulin-dependent protein kinase kinase 2 (CAMKK2)." (PMID 35741020, 2022). "Yet, GATA2 was found to regulate a set of AR-independent genes in a castration-resistant and chemotherapy-resistant xenograft model of prostate cancer." (PMID 36212399, 2022). "We first determined the direct binding between darolutamide and the AR in living prostate cancer cells in a label-free context using the cellular high throughput thermal shift assay (CETSA HT)." (PMID 36611998, 2022). "Androgens modulate a wide range of biological responses in the human body through AR and AR became a significant therapeutic target in prostate cancer treatment." (PMID 36613955, 2022). "The androgen receptor (AR) signalling pathway is the key driver in most prostate cancers (PCa), and is underpinned by several kinases both upstream and downstream of the AR." (PMID 35326402, 2022). "MicroRNAs, for example, miR-34, miR-205, and miR-320, have been reported to modulate the expression of AR in prostate cancer." (PMID 35053220, 2022). "Prostate cancer (PCa) progression relies on androgen receptor (AR) function, making AR a top candidate for PCa therapy." (PMID 35612714, 2022). "Hormonal therapies for prostate cancer target the androgen receptor (AR) ligand-binding domain (LBD)." (PMID 35053548, 2022). "Prostate cancer depends on the androgen receptor (AR), a transcriptional factor critical for prostate cancer growth and progression." (PMID 35372068, 2022). "Besides circulating biomarkers, recognizing the distinct genetic features within metastatic prostate cancer, through testing for AR splice variants (AR-Vs) or tumor suppressor genes (TSGs), might also lead to prognostic and predictive biomarkers for precision medicine." (PMID 35669415, 2022). "In contrast, silencing of AR signals can potentially be applied as a new therapeutic approach for numerous cancers besides prostate cancer." (PMID 36235203, 2022). "On the other hand, the expressions of IGSF1 and CRISP3 are known to be androgen receptor (AR)-dependent and characteristic in prostate cancer cells." (PMID 35976950, 2022). "Paradoxically, activation of AR can also inhibit the growth of prostate cancer in some patients and experimental systems, but the mechanisms underlying this phenomenon are poorly understood." (PMID 36923279, 2022). "It would be useful to repeat this experiment in similar prostate cancer cell lines such as AR-positive VCaP cells and androgen-insensitive DU-145 cells." (PMID 35447901, 2022).
prostate carcinoma (continued). "De novo motif and binding analysis for the regulation of transcription (BART) analyses of AU-15330-compacted sites identified DNA-binding elements for major oncogenic transcription factors in prostate cancer, including AR, FOXA1, HOXB13 and ERG." (PMID 34937944, 2022). "Overall, the “dual-modified” AR allows prostate cancer to evolve through two distinct therapy resistances, androgen deprivation, and AR antagonism." (PMID 35704598, 2022). "Intriguingly, overexpression of the AR NTD was reported to delay progression of prostate cancer tumors and CRPC." (PMID 34986150, 2022). "Androgen Receptor (AR) is a critical driver of prostate cancer metastases and sustains metastatic disease; however, the majority of bone metastases are castration resistant and unresponsive to AR targeted therapy." (PMID 35948987, 2022). "Genome alterations impacting non-AR pathways can also lead to late-stage, treatment-resistant prostate cancer." (PMID 35205640, 2022). "Recent observations indicate that AR function is somewhat lost at early prostate cancer stages and regained in a pathological manner at later stages." (PMID 36551650, 2022). "Preclinical data have demonstrated the ability from abemaciclib to enhance effective senescence in prostate cancer cells expressing AR." (PMID 36551557, 2022). "It has been well-established that AR is the backbone of prostate cancer tumorigenesis by facilitating cell survival, proliferation, migration, and invasion." (PMID 36551557, 2022). "Their study resulted in the discovery of PROTAC 11, which effectively induced degradation of AR protein in AR + LNCaP, VCaP, and 22Rv1 prostate cancer cell lines with DC50 values of 0.2–1 nM." (PMID 35702041, 2022). "Primary prostate cancer is androgen receptor (AR) signalling dependent; metastatic disease is treated with some form of androgen deprivation therapy (ADT)." (PMID 35354884, 2022). "Unfortunately, prostate cancer can alter AR during treatment, into incurable and lethal prostate cancer." (PMID 35935969, 2022). "AR gene aberrations are rare in prostate cancer before primary hormone treatment but emerge with castration resistance." (PMID 35402245, 2022). "Based on the experience of treating prostate cancer, the possible involvement of AR in the pathogenesis of breast cancer has attracted consideration from investigators." (PMID 35053220, 2022). "Together, this line of evidence presents HER2 kinase activity, as well as VEGF and TGF-β signaling, as key molecular events for optimal transcriptional activity of AR in prostate cancer cells." (PMID 35740556, 2022). "Until now, the approval has been limited to patients with PSMA-positive metastatic castration-resistant prostate cancer who have previously received other therapy options (such as inhibition of the androgen receptor pathway and taxane-based chemotherapy)." (PMID 36297404, 2022). "Longer survival times for prostate cancer patients due to efficient treatments consisting of local radiotherapy, prostatectomy and androgen-deprivation therapy, as well as androgen-receptor-targeted agents, increases the importance of side effect management." (PMID 35406556, 2022). "For most prostate cancer cells to grow, androgens need to bind to a cellular protein called the androgen receptor (AR)." (PMID 35456428, 2022). "AR regulates the expression of genes that play an important role in prostate cancer such as KLK3, KLK2, TMPRSS2-ERG, IGFR-1, FKBP5, FOXp1, TACC2, and UGT1A1." (PMID 36551557, 2022). "Breast cancer patients were treated with cyclin D kinase 4/6 inhibitors and hormonal therapy, ovarian cancer patients were treated with poly (ADP-ribose) polymerase inhibitors and prostate cancer patients were treated with an androgen receptor targeted agent." (PMID 36146552, 2022).